GAS5 (growth arrest specific 5)
Diseases named in the same sentence as GAS5 in open-access papers (continued):
Sharing a sentence is not in itself a finding about the gene and the disease.
rheumatoid arthritis (18 papers, 2018 to 2025). A chronic, systemic autoimmune disorder characterized by inflammation in the synovial membranes and articular surfaces. "The primary aim of this study is to investigate the relationship between Humanin levels and peripheral endothelial dysfunction in patients with rheumatoid arthritis, with a secondary focus on correlating GAS5, miR-21, and miR-103 expression levels." (PMID 39846683, 2025). "In a similar fashion, GAS5 reduces the severity of rheumatoid arthritis (RA) through sponging miR-361-5p, a process which upregulates PDK4, ultimately limiting synovial hyperplasia and cell proliferation." (PMID 39941145, 2025). "Nevertheless, altered expression of GAS5 has been reported in diseases other than cancer, including neurogenerative disorders (i.e., Alzheimer’s), autoimmune diseases (i.e., rheumatoid arthritis), knee osteoarthritis, and preeclampsia." (PMID 37444428, 2023). "It has been reported that lncRNA GAS5 is downregulated in rheumatoid arthritis and osteoarthritis, and its downregulation contributes to the disease progression." (PMID 34936242, 2022). "lncRNA growth arrest‐specific transcript 5 (GAS5) has been proven to be involved in rheumatoid arthritis." (PMID 34936242, 2022). "Recent studies by Wang and Peng reported the role of GAS5 in hypoxic-ischemic brain damage and rheumatoid arthritis progression via the miR-128-3p/BAX axis and miR-128-3p/HDAC4 axis." (PMID 36672566, 2022). "As reported in the literature, GAS5 seems to play a role in various inflammatory and autoimmune diseases such as rheumatoid arthritis and systemic lupus erythematosus in which significantly reduced GAS5 levels in immune cells were shown." (PMID 31652976, 2019). "Notably, GAS5 is dysregulated in prominent inflammatory disorders, such as rheumatoid arthritis, systemic lupus erythematosus, multiple sclerosis, and sarcoidosis." (PMID 39941145, 2025). "RNA-growth arrest-specific transcript 5 (GAS5) is an lncRNA located on chromosome 1q25.1 with many functions in inflammatory and autoimmune diseases such as rheumatoid arthritis (RA) and systemic lupus erythematosus (SLE)." (PMID 34485536, 2021). "With regard to lnc‐GAS5, miR‐21, and miR‐140 expression in immune diseases, previous studies have shown that lnc‐GAS5 expression is increased in T cells in patients with rheumatoid arthritis (RA) compared to that in individuals without RA." (PMID 34473845, 2021). "Furthermore, an investigation of lncRNA expression in rheumatoid arthritis fibroblast-like synoviocytes (RAFLS) following the administration of quercetin found, among other things, differential expression of MALAT1, HOTAIR, MEG3, CBR3-AS1, GAS5 and YIYA." (PMID 29751665, 2018).
Hypertension (17 papers, 2017 to 2025). The presence of chronic increased pressure in the systemic arterial system. "Multivariate regression models adjusted for cardiorenal confounders (hypertension, blood pressure, and so on) evaluated GAS5’s association with fibrosis." (PMID 40685500, 2025). "For the first time, the findings presented here suggest that the NEAT1, HOTAIR, and GAS5 are novel diagnostic and prognostic markers for stroke associated with hypertension." (PMID 36439973, 2023). "In particular, lncRNA-GAS5 (growth arrest-specific 5) has been identified as a regulator of hypertension-induced vascular remodelling, which when knocked down causes hypertension." (PMID 29394331, 2018). "The lncRNA GAS5 (growth arrest-specific 5) regulates vascular remodelling in hypertension and is expressed primarily in ECs and VSMCs." (PMID 37371099, 2023). "LncRNAs NEAT1, GAS5, and HOTAIR have previously been linked to the risk and development of CVS, and to pathologic vasculature remodeling in response to hypertension, which is the primary risk factor for cerebrovascular dysfunction." (PMID 36439973, 2023). "Another lncRNA, GAS5 (growth arrest-specific 5) plays a role in regulating vascular remodeling in hypertension, with primary expression in endothelial cells (ECs) and VSMCs." (PMID 37987360, 2023). "For example, growth arrest-specific long non-coding RNA 5 (GAS5) is one of the best studied lncRNAs involved in the pathogenesis of hypertension and vascular remodeling." (PMID 36187570, 2022). "Similarly, GAS5 plays an essential role in vascular remodeling during arterial hypertension, and it is a crucial regulator of apoptosis and proliferation of VSMCs by inhibiting β-catenin signaling and/or miR-21." (PMID 36439973, 2023). "Vascular remodelling in arterial hypertension is regulated by GAS5 and AK0986656 lncRNAs." (PMID 37371099, 2023). "GAS5 inhibits PDGF–BB-induced VSMC proliferation and migration, partly by acting as a ceRNA of miR-21, providing new evidence that GAS5 may serve as a potential therapeutic target for hypertension." (PMID 35328496, 2022). "For example, in hypertension, GAS5 has been considered as a new vascular remodeling regulator." (PMID 34698362, 2021). "In addition, lncRNA GAS5 knockdown can aggravate the microvascular dysfunction induced by hypertension, affecting VSMC phenotypic transformation." (PMID 34386495, 2021). "Examples include AK098656, which promotes hypertension through regulation of vascular smooth muscle cells (VSMCs) functions, GAS5, which promotes vascular remodeling and is downregulated in hypertension, and the TUG1/miR-145-5p/FGF10 axis, which regulates proliferation and migration in VSMCs." (PMID 32392180, 2020). "In terms of SMC phenotypic switching, lncRNA-growth arrest-specific 5 (GAS5) was reported to be involved in hypertension-related vascular remodeling via changes in endothelial activation and proliferation, SMC phenotype conversion, and EC-VSMC communication, primarily through β-catenin signaling." (PMID 28670289, 2017). "After adjusting for factors such as hypertension history, systolic and diastolic blood pressure, blood urea nitrogen, creatinine, eGFR, and uric acid, use of ACEI/ARB, multivariate analysis showed significant associations between urinary GAS5 level and renal fibrosis." (PMID 40685500, 2025). "LncRNA GAS5, mainly expressed in ECs/VSMCs, was also suggested to participate in hypertension via modulating multiple links such as EC proliferation, VSMC phenotype conversion, and EC-VSMC communication by β-catenin signaling; knockdown of GAS5 could aggravate microvascular dysfunction." (PMID 31355277, 2019). "ROC curve analysis for the NEAT1, HOTAIR, and GAS5 revealed statistically significant differences in CVS patients, whether they had hypertension or not, when compared to controls, with fair sensitivity and high specificity, implying their diagnostic values." (PMID 36439973, 2023).
liver fibrosis (17 papers, 2016 to 2025). "Before cirrhosis develops, elevated levels of the circulating lncRNA GAS5 are linked to liver fibrosis." (PMID 40868128, 2025). "NME2 is a histidine kinase involved in TGF-β–induced activation of hepatic stellate cells, a liver pericyte prototype, and CCl4-induced liver fibrosis, and Gas5 is a long noncoding RNA whose high levels are associated with liver fibrosis." (PMID 36136606, 2022). "The results demonstrated that lncRNA-H19, -MALAT1, -PVT1, -P21 and -GAS5 all participated in liver fibrosis formation after schistosome infection." (PMID 39044218, 2024). "This study reveals the dynamic role of lncRNA-H19, -MALAT1, -PVT1, -P21, and -GAS5 in HSCs activation and liver fibrosis in S. japonicum-infected mice, regulated by the ICOSL/ICOS signaling pathway." (PMID 39044218, 2024). "In summary, both ATG and GAS5 present promising approaches to inhibit HSC proliferation in the context of liver fibrosis." (PMID 38511056, 2024). "Concurrently, growth arrest-specific 5 (GAS5) and exosomes produced from bone marrow mesenchymal stem cells exerted an inhibitory effect on liver fibrosis." (PMID 39300122, 2024). "In another study, a different researcher explored the role of the lncRNA growth arrest-specific transcript 5 (GAS5) in the regulation of liver fibrosis." (PMID 38511056, 2024). "The progression of fibrosis was linearly correlated with plasma GAS5 expression, which also suggests the potential of plasma GAS5 as a noninvasive marker of liver fibrosis in patients with NAFLD." (PMID 34899344, 2021). "Altogether, circulating elevated lncRNA GAS5 levels correlated with the progression of liver fibrosis prior to the development of cirrhosis can be used to serve as a valid non-invasive marker in patients with NAFLD and CHB with liver fibrosis." (PMID 34899344, 2021). "In conclusion, we found that as liver fibrosis progressed, plasma and tissue GAS5 levels increased, whereas the development of cirrhosis was associated with the downregulation of plasma GAS5 in patients with NAFLD." (PMID 32413995, 2020). "MEG3 and GAS5 can inhibit liver fibrosis, while TUG1 can protect liver grafts during cold preservation." (PMID 31828106, 2019). "Notably, lncRNA-H19, -MALAT1, and -PVT1 are positively correlated with liver fibrosis, while lncRNA-P21 and -GAS5 are potential inhibitors of the liver fibrosis process." (PMID 39044218, 2024). "This is based on the previous observations that downregulation of elevated PI3K-AKT-mTOR signaling, via miR-101, lncRNA GAS5 and miR-23a or miR-29a, resulted in reducing the extent of chronic liver damage by decreasing hepatic stellate cells activation and liver fibrosis." (PMID 34572126, 2021). "Thus, the ability of lncRNA GAS5 to act as a sponge platform for miR-23a and competitively reduce the expression level of miR-23a to inhibit liver fibrosis can be confirmed." (PMID 34899344, 2021). "In addition, another recent study reported that lncRNA GAS5 plays the role of sponge for miR-23a to repress hepatic fibrosis via the PI3K/Akt/mTOR pathway and upregulation of Snail in the CCl4-induced rat model." (PMID 32413995, 2020). "However, as liver fibrosis progressed towards cirrhosis, plasma GAS5 was seen to be abruptly downregulated in the present study, similar to the results of the previous investigation." (PMID 32413995, 2020). "In addition, to evaluate its changes during the progression of fibrosis, GAS5 expression was analyzed according to the liver fibrosis stage." (PMID 32413995, 2020). "We believe that the suppressive effect of GAS5 on liver fibrosis may be maintained until the development of cirrhosis." (PMID 32413995, 2020). "However, contrary to previous observations, we found that the expression of GAS5 positively correlated with the progression of liver fibrosis." (PMID 32413995, 2020). "Also, they found that as liver fibrosis progressed, plasma and tissue GAS5 levels increased." (PMID 40868128, 2025).
liver fibrosis (continued). "Conversely, lncRNA-P21 and -GAS5 may inhibit liver fibrosis by regulating specific miRNAs." (PMID 39044218, 2024). "Furthermore, small interfering RNA transfection (siRNA) in JS-1 cells in vitro confirmed that lncRNA-H19, -MALAT1, and -PVT1 promoted liver fibrosis, whereas lncRNA-P21 and -GAS5 had the opposite effect on key fibrotic molecules, including α- smooth muscle actin and collagen I expression." (PMID 39044218, 2024). "Thus, it can be hypothesized that plasma GAS5 might be increased to compensate advanced fibrosis for regression of liver fibrosis." (PMID 32413995, 2020). "In contrast, they showed enhanced expression of lncRNA-P21 and -GAS5 compared with C57BL/6 mice, influencing liver fibrosis development." (PMID 39044218, 2024). "Of these ceRNA mechanisms, LincRNA-p21 /MicroRNA-17-5p, lncRNA GAS5/miR-23a, LncRNA Gm5091/miR-27b/23b/24, and MALAT1/miR-101b have been suggested to contribute to the alleviation of liver fibrosis." (PMID 35902883, 2022). "In a model of liver fibrosis, overexpression of GAS5 (growth arrest-specific transcript 5) increased p27Kip1 protein levels acting as a ceRNA for miR-222, thereby inhibiting the activation and proliferation of primary hepatic stellate cells and fibrogenesis." (PMID 35456025, 2022). "Like GAS5, lncRNA, including lncRNA-p21, PVT1, HOTAIR, and MALAT1, acts as a ceRNA regarding liver fibrosis." (PMID 32413995, 2020). "The roles of GAS5 in benign liver disease have been reported in hepatitis C virus (HCV) replication and liver fibrosis." (PMID 32413995, 2020). "Several lncRNAs, including MEG3, GAS5, Gm5091, NR_002155.1, and HIF1A-AS1, have been demonstrated to inhibit liver fibrosis." (PMID 32098245, 2020). "Intriguingly, lncRNA GAS5 acts as a sponge platform to competitively decrease miR-23a expression, and miR-23a degrading PTEN further influenced the downstream pathway PI3K/Akt/mTOR/Snail in hepatic fibrosis." (PMID 33240872, 2020). "Consequently, the lncRNA GAS5/miR-23a/PTEN/PI3K/Akt/mTOR/Snail and GAS5/miR-222/p27 signalling pathways can provide molecular targets for the treatment of liver fibrosis." (PMID 32098245, 2020). "Previous investigations demonstrated that overexpression of lncRNAs such as H19, maternally expressed gene 3 (MEG3), growth arrest-specific transcript 5 (GAS5), Gm5091, NR_002155.1, and HIF 1alpha-antisense RNA 1 (HIF1A-AS1) can inhibit the progression of liver fibrosis." (PMID 32098245, 2020). "The results of qRT PCR analysis suggested lower serum lncRNA GAS5 levels in CHB patients, and the results of ROC curve analysis showed that serum lncRNA GAS5 could effectively differentiate between CHB liver fibrosis patients and healthy controls (AUC of 0.993, 0.972–0.992)." (PMID 34899344, 2021).
myocardial infarction (17 papers, 2019 to 2025). Gross necrosis of the myocardium, as a result of interruption of the blood supply to the area, as in coronary thrombosis. "The results of this study demonstrated that lncRNA GAS5 was significantly upregulated in hypoxia-injured H9c2 cells and its expression inhibited the progression of heart failure caused by myocardial infarction." (PMID 38250803, 2023). "The aberrant expression of GAS5 and miR-21 is associated with cardiovascular disease and dysfunctions such as cardiac fibrosis, acute myocardial infarction, increased cardiomyocyte damage and apoptosis, and the aberrant proliferation and migration of vascular smooth muscle cells." (PMID 39941145, 2025). "Moreover, lncRNA GAS5 (Long non-coding RNA Growth Arrest-Specific 5), which is known as a tumor suppressor gene, has been implicated in heart failure caused by myocardial infarction." (PMID 38250803, 2023). "In the context of myocardial infarction, GAS5 was demonstrated to ameliorate cardiomyocyte apoptosis and reduce infarct size in vivo by negatively regulating semaphorin 3a (sema3a)." (PMID 39941145, 2025). "One study regarding myocardial infarction suggested that by sponging miR-525-5p, GAS5 enhances the expression of calmodulin 2 (CALM2) and induces the apoptosis of myocardial cells, thereby promoting the development and progression of myocardial infarction." (PMID 39941145, 2025). "GAS5 regulates the proliferation, cell cycle and proliferation of myocardial infarction (MI) cells and its overexpression can lead to increased susceptibility to MI44." (PMID 38167627, 2024). "GAS5 also reportedly plays a key regulatory role in the pathogenesis of cardiovascular diseases such as coronary artery disease, myocardial infarction, coronary atherosclerosis, and diabetic cardiomyopathy." (PMID 38812041, 2024). "Our results indicate that GAS5 can regulate the process of myocardial infarction (MI) by targeting the miR‐21/PTEN axis." (PMID 37506155, 2023). "Recently, a growing body of evidence has indicated that GAS5 is also involved in cardiovascular pathologies such as cardiac hypertrophy, myocardial infarction, and myocardial apoptosis." (PMID 37569470, 2023). "Evidence demonstrated that aerobic exercise can decrease cardiomyocytes' apoptosis and heart fibrosis areas following MI via modulating the expressions of myocardial infarction associated transcript (MIAT), H19, and lncRNA GAS5." (PMID 36440025, 2022). "For example, MALAT1 knockout can alleviate acute myocardial infarction through the miR-320/Pten axis, and lncRNA Gas5 targets the miR-525-5p/CALM2 axis to regulate myocardial infarction." (PMID 35005241, 2021). "Meanwhile, down‐regulation of GAS5 limited myocardial infarct size and reduced apoptosis in I/R‐heart." (PMID 31625671, 2019). "Previous studies have shown that GAS5 plays a regulatory role in the pathological process of a series of cardiovascular diseases such as hypertrophic cardiomyopathy and myocardial infarction, yet its role in AF remains unclear." (PMID 37569470, 2023). "LncRNA Gas5 regulates myocardial infarction by targeting the miR-525-5p/CALM2 axis." (PMID 36061542, 2022). "Likewise, silencing of GAS5 has been found to improve the cardiac function, alleviate pathological injury, and decrease myocardial cell death in mice with acute myocardial infarction." (PMID 33645622, 2021). "Here, patients with high expression levels of KIAA0495 showed shorter survival, while patients with low expression levels of PART1, MGC21881, myocardial infarction-associated transcript (MIAT), growth arrest-specific 5 (GAS5), and Prader Willi/Angelman region RNA 5 (PAR5) showed prolonged survival." (PMID 32650527, 2020).
renal cell carcinoma (16 papers, 2014 to 2024). "GAS5 and miR-34a were positively correlated in renal cell carcinoma, however further studies are required to explore the effect of GAS5 on mitochondrial metabolism of renal cell cancer." (PMID 38544804, 2024). "However, lncRNA GAS5 played an inhibiting role in renal cell carcinoma." (PMID 36033389, 2022). "GAS5 functions as a competing endogenous RNA to repress miR-21, which regulates its downstream target SOX5, resulting in the sensitivity of renal cell carcinoma to sorafenib." (PMID 37296859, 2023).